APOA1 (apolipoprotein A1)
Diseases named in the same sentence as APOA1 in open-access papers (continued):
Sharing a sentence is not in itself a finding about the gene and the disease.
transmissible spongiform encephalopathies (1 paper, 2011). "Several studies have also reported the involvement of many members of the apolipoprotein gene family (ApoA1, ApoA4, ApoC1, ApoC2, ApoC3 and ApoD) in transmissible spongiform encephalopathies." (PMID 21629698, 2011).
tubulovillous adenoma (1 paper, 2020). An epithelial neoplasm morphologically characterized by the presence of a villous and a tubular architectural pattern. "Among patients with tubulovillous adenomas, those with recurrence had a higher TG level and TG/HDL (P < 0.05) and lower HDL and ApoA1 levels (P < 0.05)." (PMID 32967679, 2020).
uremia (1 paper, 2015). A clinical syndrome associated with the retention of renal waste products or uremic toxins in the blood. "In addition to uremia, smoking is another cause of high plasma thiocyanate, which oxidizes to form cyanate and catalyzes ApoA1 carbamylation." (PMID 26090384, 2015). "ApoA1 in uremia patients has been reported to be heavily carbamylated due to the presence of high plasma urea levels." (PMID 26090384, 2015).
vaginal cancer (1 paper, 2004). A primary or metastatic malignant neoplasm involving the vagina. "Similarly, in this study, we observed high expression of HSP 27, GST and Apolipoprotein A1 in both cervical and vaginal cancers compared with normal vaginal tissue." (PMID 15199389, 2004).
varicocele (1 paper, 2015). A condition characterized by the dilated tortuous veins of the spermatic cord with a marked left-sided predominance. "The low expression of APOA1 is indicative of its possible role in sperm motility, as shown by the poor sperm motility in varicocele patients." (PMID 25890347, 2015). "We found that APOA1 preprotein was underexpressed in the unilateral varicocele patient group and showed very low abundance." (PMID 25890347, 2015).
venous thromboembolism (1 paper, 2026). Occlusion of the lumen of a vein by a thrombus that has migrated from a distal site via the blood stream. "This population-based cohort investigated the association between HDL subfractions (particle size, concentration, and lipid composition), ApoA1, and the risk of future venous thromboembolism." (PMID 41552750, 2026).
Vestibular schwannoma (1 paper, 2024). A vestibular schwannoma (also known as acoustic neuroma, acoustic neurinoma, or acoustic neurilemoma) is a benign, usually slow-growing tumor that develops from the VIIIth cranial nerve supplying the inner ear. "The association of elevated HDL cholesterol and apolipoprotein A1 levels with an increased risk of sporadic vestibular schwannoma presents a paradox within the context of the role of lipid metabolism in tumorigenesis." (PMID 39621164, 2024).
cardiovascular disease (217 papers, 2006 to 2025). "Multiple studies have identified an association of ApoA-1 or ApoA-1:lipid ratio and cardiovascular disease." (PMID 41361833, 2025). "We found Apolipoprotein A1 (ApoA-1) was associated with decreased hazards of cardiovascular disease (HRmeasured protein:0.79, P = 0.001, HREpiScore: 0.71, P = 4.76 × 10− 06) in the age and sex adjusted model." (PMID 41361833, 2025). "Prior research has demonstrated that the APOB/APOA1 is a risk factor for cardiovascular disease and is associated with an unfavorable prognosis for cardiovascular disease." (PMID 40787622, 2025). "Recent studies have shown that ApoA1 and ApoB are more accurate predictors of cardiovascular disease risk." (PMID 39931360, 2025). "Anti-ApoA-1 IgG has emerged as a noteworthy biomarker associated with cardiovascular disease (CVD) and mortality." (PMID 39752005, 2025). "Apolipoprotein is a constituent of lipoproteins, and its ratio levels (ApoB/ApoA1 ratio) are considered an independent risk factor for cardiovascular diseases." (PMID 39081429, 2024). "Conversely, changes of HDL-C [MD = 6.27, CI (5.17 to 7.36), P < 0.00001] and ApoA1 [MD = 4.33, 95% CI (3.53 to 5.13), P < 0.00001] from baseline were significantly more in high cardiovascular disease risk patients who received PCSK9 inhibitors treatment." (PMID 35529059, 2022). "For example, a study in Chinese diabetic patients showed that the ApoB/ApoA1 ratio predicted cardiovascular disease risk in men." (PMID 36016824, 2022). "The ratio of apolipoprotein B100 to apolipoprotein A1 (ApoB100/ApoA1), a strong independent risk factor for cardiovascular diseases, was significantly increased." (PMID 34938772, 2021). "ApoA1 concentrations are inversely and ApoB levels are positively correlated with the risk of cardiovascular diseases." (PMID 34444289, 2021). "Cortisol regulates the metabolism of mouse adipose cells through the serotonin receptor gene HTR2C, and genetic variation of the APOA1 gene is linked to lipid metabolism and cardiovascular disease risk." (PMID 33934713, 2021). "A low ApoA1 expression level indicates an increased risk of cardiovascular disease, especially in the presence of exaggerated pro-thrombotic features of blood platelets." (PMID 33086557, 2020). "Increasing evidence has shown that elevated levels of serum apolipoprotein B100 (apoB), as well as decreased levels of serum apolipoprotein A1 (apoA1), are both independent risk factors for cardiovascular diseases (CVD)." (PMID 32546165, 2020). "For example, the ApoB/apoA-1 ratio has been proposed as a simple, accurate risk factor for cardiovascular disease —the lower the apoB/apoA-I ratio, the lower is the risk." (PMID 29423541, 2018). "Ratios associated with increased cardiovascular disease risk were also negatively correlated with the HCV RNA:apoB/apoA-1 ratio (r = − 0.490; p = 0.015), TG/HDL-C ratio (r = − 0.450; p = 0.031) and total cholesterol/HDL-C ratio (r = − 0.450; p = 0.027)." (PMID 29423541, 2018). "ApoE despite apoA1 is associated with cardiovascular disease due to formation of cholesterol plaques within the arteries." (PMID 28695482, 2017). "The binding of Hp to apolipoprotein A1 (ApoA1) has also been reported to be related to the T2DM-associated cardiovascular disease." (PMID 28758129, 2017). "Anti-apoA-1 antibodies have thus attracted particular interest as a possible mediator between inflammation and the recognised increased risk of developing cardiovascular disease (CVD) in patients with SLE." (PMID 25890187, 2015). "APOA1 is the major component of high density lipoprotein in plasma and SNPs in APOA1 gene have been associated with the risk of cardiovascular diseases and with T2D." (PMID 24868529, 2014). "We propose some apolipoprotein A1 fractions as a possible new disease-associated marker of cardiovascular disorders." (PMID 21631938, 2011).
cardiovascular disease (continued). "Many of the identified proteins are known markers, risk factors, or proteins known to be involved in cardiovascular disease; e.g. transthyretin, apoA1, fibrinogen, serum amyloid A protein, haptoglobin, plasminogen, and others." (PMID 21631938, 2011). "Low plasma APOA1 levels have been associated with an increased risk of cardiovascular disease." (PMID 40891102, 2025). "APOA1 particles can increase cholesterol efflux from cells and risk for cardiovascular disease." (PMID 40943443, 2025). "The authors suggested that an elevated ApoB/ApoA1 ratio may be independently related to cardiovascular disease and all-cause mortality." (PMID 38393015, 2024). "A higher ratio of apoB to apoA1 is a recognized risk factor for cardiovascular disease." (PMID 36542145, 2023). "Another clinical study demonstrated that consumption of raw tomato (200 g/day) could prevent type 2 diabetes‐associated cardiovascular diseases by lowering systolic and diastolic blood pressure, upregulating ApoA1, and downregulating ApoB levels." (PMID 37823149, 2023). "As Apolipoprotein-A1 seems to be cardioprotective and a reduction in Apolipoprotein-A1 correlates with a higher risk for cardiovascular disease, this might be a sign of the detrimental effects of HRE in athletes on the cardiovascular system." (PMID 36420357, 2022). "The ApoB/ApoA1 ratio is a strong and new risk factor for cardiovascular disease (CVD)." (PMID 34996506, 2022). "Previous studies have shown that ApoA1 levels are associated with cardiovascular diseases." (PMID 33336932, 2021). "An unbalanced lipid profile with high total cholesterol (TC), low-density lipoprotein-cholesterol (LDL-C), triglycerides (TG), and low high-density lipoprotein-cholesterol (HDL-C), apolipoprotein A1(Apo-A1), apolipoprotein B (Apo-B) is an established risk factor of cardiovascular diseases." (PMID 29678178, 2018). "Multiple adverse health outcomes have been linked to low apoA1 levels, high apoB levels and high apoB/apoA1 ratios, leading to interest in developing strategies to manage abnormal apo variables for the prevention or treatment of associated metabolic and cardiovascular diseases." (PMID 29312456, 2018). "The apoB/apoA1 ratio is also a marker of risk for future cardiovascular disease." (PMID 29017497, 2017). "Elevated levels of the MPO-oxidized apoA1 form, oxTrp72-apoA1, in subjects are thus associated with increased cardiovascular disease risk, and may serve for monitoring a pro-atherogenic process in the artery wall." (PMID 29270905, 2017). "Based on this finding, Sun and coworkers suggested that high apoA1 content might be associated with increased risk of cardiovascular disease." (PMID 27160764, 2016). "Interestingly, the ratio of APOB to APOA1, which is used to assess cardiovascular disease risk, decreased due to weight loss by 8% and remained lower over time (week 52: 7%) for 25 of the 42 study participants." (PMID 28007936, 2016). "Therefore, we propose the high MW apoA1 fraction as a possible new disease-associated marker of cardiovascular disorders." (PMID 21631938, 2011). "Despite the low number of replicates (n = 20, each group) and the observed variability of band intensities, we assume that the high MW apoA1 fraction might be a new disease-associated marker of cardiovascular disorders." (PMID 21631938, 2011). "Apolipoproteins have been demonstrated to play physiological roles on nutrition transport and energy metabolism, and numerous variants have been revealed in some apolipoproteins including ApoA1, ApoA5, ApoB, ApoC3 and ApoE, which are associated with the risk of cardiovascular disease." (PMID 21799896, 2011). "Their Lp(a) and ApoB levels were slightly above the upper limits of normal (38 ± 34 and 112 ± 24 mg/dL), while the ApoA1 levels were with in normal limits (166 ± 28 mg/dL), attesting to a normal lipoprotein metabolism, with an average cardiovascular disease risk." (PMID 20659335, 2010).
cardiovascular disease (continued). "In addition to its potential protective effects on the cardiovascular system and lowering of cardiovascular disease risk, accumulating evidence over the past decade supports the multifunctional nature of APOA1 with immunity, anti-inflammation, apoptosis, anti-clotting and anti-aggregatory effects." (PMID 33953300, 2021). "Naturally occurring mutations can disrupt normal APOA1 folding and self-association, leading to dysfunctional HDL formation and cardiovascular disease." (PMID 41167396, 2025). "Among lipids, HDL, with its backbone ApoA1, produced in hepatocytes and known to protect against cardiovascular diseases, was reduced." (PMID 39909798, 2025). "APOB/APOA1, as a novel lipid parameter, shows a unique clinical value in the field of cardiovascular disease." (PMID 40787622, 2025). "Autoantibodies against the main protein component of high-density lipoprotein (HDL) and apolipoprotein A-1 (anti-ApoA-1 IgG) have become recognized as an independent biomarker for cardiovascular disease and death throughout the last 10 years." (PMID 39752005, 2025). "The ApoB/ApoA1 ratio has been identified as associated with T2DM independently, particularly in patients with cardiovascular disease, potentially serving as a predictor of cardiovascular risk in these cases." (PMID 38393015, 2024). "APOA1 is involved in cholesterol metabolism and cardiovascular disease, but its role in reproduction is unclear and needs to be further explored." (PMID 38731262, 2024). "We identified a common reduction in ApoA1 (HDL) and elevated GlycA levels over age in SLE associated with serological measures of disease activity and cardiovascular disease risk." (PMID 38048621, 2024). "Apolipoprotein A‐1 (ApoA1) is a component of HDL that is involved in cardiovascular disease prevention by regulating blood cholesterol levels." (PMID 38018577, 2023). "Patients with cardiovascular disorders can be clinically tested for apolipoprotein-A1 (Apo-A1) using an ELISA immunoassay." (PMID 37375810, 2023). "While APOA1 is recognized for its role in cardiovascular disease, an in vitro study carried out in mice proved that APOA1 has anti-tumorigenic roles; mice with the human APOA1 transgene (A1Tg) experienced hindered cancer growth and progression." (PMID 38067270, 2023). "As such, higher levels of HDL and apoA1 have been shown to be protective against conditions such as cardiovascular disease." (PMID 37372137, 2023). "While most studies investigated the expression and functions of ApoA1 in cardiovascular diseases and lipid metabolism, the impacts of ApoA1 in SAE remain to be explored." (PMID 36600206, 2023). "Subsequent studies added further support to the link between anti-apoA-1 IgG and cardiovascular disease." (PMID 34888742, 2022). "The apolipoprotein B/apolipoprotein A1 (ApoB/ApoA1) ratio is recognized as a clinical indicator of cardiovascular disease and ischemic cerebral disease." (PMID 32017458, 2020). "In particular, subjects in the C-IFG/IGT subtype showed an increased risk of cardiovascular disease, as evidenced by increased LDL/HDL and cholesterol/HDL ratios and decreased HDL and ApoA1 levels." (PMID 32295016, 2020). "Autoantibodies against apolipoprotein A-1 (anti-apoA-1 IgG) have emerged as an independent biomarker for cardiovascular disease and mortality in several populations." (PMID 29423541, 2018). "Autoantibodies against apolipoprotein A-1 (anti-apoA-1 IgG) have emerged as an independent biomarker for cardiovascular disease and mortality." (PMID 28458671, 2017). "There is a growing body of evidence indicating that apoB/apoA-1 is a powerful biomarker of future cardiovascular disease as it impacts lipid metabolism, and is a marker of inflammation possessing both anti-oxidant and anti-inflammatory effects." (PMID 28810853, 2017). "As such, the apoB/apoA-1 -ratio appears to be a better marker for cardiovascular diseases than traditional lipids or lipid ratios." (PMID 28837598, 2017).
cardiovascular disease (continued). "As a major protein constituent of high density lipoprotein, ApoA-1 plays an important role in protecting against cardiovascular diseases because of its anti-atherogenic function." (PMID 27683106, 2016). "ApoA-1, which is generally considered to protect against cardiovascular disease, has been reported to exhibit a unique effect on tumor progression in recent studies." (PMID 27683106, 2016). "Does positivity for IgG anti-apoA-1 early in the disease course predict subsequent damage, cardiovascular disease and/or mortality?" (PMID 25890187, 2015). "We also found that smoking was associated with unfavorable changes in the levels of apoA1 and apoB and in estimated HDL and LDL particle size, thereby providing a new pathophysiological mechanism linking smoking to increased risk of cardiovascular disease." (PMID 24228807, 2013). "ApoA1 is the major protein component of HDL-C in plasma, which has a role in protection against cardiovascular disease associated with HDL-C." (PMID 23451155, 2013). "High levels of apoA1 can help to prevent heart disease, and it has also been shown that apoA1 plasma level is decreased in cardiovascular disease." (PMID 21631938, 2011). "Several studies further supported the link between anti-apoA-1 IgG and cardiovascular disease." (PMID 39752005, 2025). "In addition to its role in regulating cholesterol and protecting against cardiovascular disease, ApoA1 also plays a significant role in inflammatory and immune responses." (PMID 40809523, 2025). "Some studies have confirmed the general risk prediction value of APOB/APOA1 in global populations and the superiority of APOB/APOA1 over HDL or LDL assays alone for early risk identification, which provides strong support for early risk identification in cardiovascular disease." (PMID 40787622, 2025). "The evidence suggests that the ApoB/ApoA1 ratio may provide a more accurate assessment of cardiovascular disease risks." (PMID 41245272, 2025). "Notably, the most prominent associated proteins were APOA1 and APOA2, crucial components of HDL and widely recognized as protective markers for cardiovascular disease." (PMID 40926231, 2025). "Although there is a significant correlation between the level of apolipoprotein A1 and PAGln, the ratio of apolipoprotein A1 and apolipoprotein B is usually used as a marker in clinical practice for the diagnosis of cardiovascular disease, with a threshold of 1.0." (PMID 36797695, 2023). "APOA1 is a common biomarker for the prediction of cardiovascular disease." (PMID 37432375, 2023). "The protective effect of moderate alcohol consumption on cardiovascular disease in the general population was previously assumed to be due to alcohol-associated increases in HDL cholesterol and apolipoprotein A1 levels, increased insulin sensitivity, and reduced platelet aggregation." (PMID 35707634, 2022). "In addition to its role in regulating cholesterol and protecting against cardiovascular disease, ApoA1 has many functions in inflammatory and immune responses." (PMID 35327501, 2022). "Auto-antibodies against apolipoprotein A1 may neutralize the cardioprotective effect of the HDL complex, causing cardiovascular disease in SLE patients with anti-apolipoprotein A1 antibodies." (PMID 33746988, 2021). "The prognostic value of ApoA1 self-antibodies in cardiovascular diseases should be highlighted." (PMID 34563206, 2021). "Moreover, NAB was found to have a beneficial effect on LDL-C, ApoA1, and DBP measurements, all known risk factors for cardiovascular disease." (PMID 34209273, 2021). "Although we found that anti-ApoA-1 IgG, a pro-inflammatory factor already validated in larger cohorts of patients suffering from cardiovascular disease, might negatively impact on gestation, larger studies are warranted to confirm these results." (PMID 32219148, 2020).